QKI (QKI, KH domain containing RNA binding)
Description:
RNA reader protein, which recognizes and binds specific RNAs, thereby regulating RNA metabolic processes, such as pre-mRNA splicing, circular RNA (circRNA) formation, mRNA export, mRNA stability and/or translation. Involved in various cellular processes, such as mRNA storage into stress granules, apoptosis, lipid deposition, interferon response, glial cell fate and development. Binds to the 5'-NACUAAY-N(1,20)-UAAY-3' RNA core sequence. Acts as a mRNA modification reader that specifically recognizes and binds mRNA transcripts modified by internal N(7)-methylguanine (m7G). Promotes the formation of circular RNAs (circRNAs) during the epithelial to mesenchymal transition and in cardiomyocytes: acts by binding to sites flanking circRNA-forming exons. CircRNAs are produced by back-splicing circularization of pre-mRNAs. Plays a central role in myelinization via 3 distinct mechanisms. First, acts by protecting and promoting stability of target mRNAs such as MBP, SIRT2 and CDKN1B, which promotes oligodendrocyte differentiation (By similarity). Second, participates in mRNA transport by regulating the nuclear export of MBP mRNA (By similarity). Finally, indirectly regulates mRNA splicing of MAG pre-mRNA during oligodendrocyte differentiation by acting as a negative regulator of MAG exon 12 alternative splicing: acts by binding to HNRNPA1 mRNA splicing factor, preventing its translation (By similarity). Involved in microglia differentiation and remyelination by regulating microexon alternative splicing of the Rho GTPase pathway (By similarity). Involved in macrophage differentiation: promotes monocyte differentiation by regulating pre-mRNA splicing in naive peripheral blood monocytes. Acts as an important regulator of muscle development: required for the contractile function of cardiomyocytes by regulating alternative splicing of cardiomyocyte transcripts (By similarity). Acts as a negative regulator of thermogenesis by decreasing stability, nuclear export and translation of mRNAs encoding PPARGC1A and UCP1 (By similarity). Also required for visceral endoderm function and blood vessel development (By similarity). May also play a role in smooth muscle development. In addition to its RNA-binding activity, also acts as a nuclear transcription coactivator for SREBF2/SREBP2 (By similarity). [Isoform QKI5]: Nuclear isoform that acts as an indirect regulator of mRNA splicing (By similarity). Regulates mRNA splicing of MAG pre-mRNA by inhibiting translation of HNRNPA1 mRNA, thereby preventing MAG exon 12 alternative splicing (By similarity). Involved in oligodendrocyte differentiation by promoting stabilization of SIRT2 mRNA (By similarity). Acts as a negative regulator of the interferon response by binding to MAVS mRNA, downregulating its expression. Also inhibits the interferon response by binding to fibrinectin FN1 pre-mRNA, repressing EDA exon inclusion in FN1. Delays macrophage differentiation by binding to CSF1R mRNA, promoting its degradation. In addition to its RNA-binding activity, also acts as a nuclear transcription coactivator for SREBF2/SREBP2, promoting SREBF2/SREBP2-dependent cholesterol biosynthesis (By similarity). SREBF2/SREBP2-dependent cholesterol biosynthesis participates to myelinization and is required for eye lens transparency (By similarity). [Isoform QKI6]: Cytosolic isoform that specifically recognizes and binds mRNA transcripts modified by internal N(7)- methylguanine (m7G). Interaction with G3BP1 promotes localization of m7G-containing mRNAs into stress granules in response to stress, thereby suppressing their translation. Acts as a translational repressor for HNRNPA1 and GLI1 (By similarity). Translation inhibition of HNRNPA1 during oligodendrocyte differentiation prevents inclusion of exon 12 in MAG pre-mRNA splicing (By similarity). Involved in astrocyte differentiation by regulating translation of target mRNAs (By similarity). [Isoform QKI7]: Cytosolic isoform that specifically recognizes and binds mRNA transcripts modified by internal N(7)- methylguanine (m7G). Interaction with G3BP1 promotes localization of m7G-containing mRNAs into stress granules in response to stress, thereby suppressing their translation. Acts as a negative regulator of angiogenesis by binding to mRNAs encoding CDH5, NLGN1 and TNFAIP6, promoting their degradation. Can also induce apoptosis in the cytoplasm (By similarity). Heterodimerization with other isoforms results in nuclear translocation of isoform QKI7 and suppression of apoptosis (By similarity). Also binds some microRNAs: promotes stabilitation of miR-122 by mediating recruitment of poly(A) RNA polymerase TENT2, leading to 3' adenylation and stabilization of miR-122.
Synonyms: Hqk; HqkI; QK3; QK; QK1
Tractability: PROTAC: UniProt records ubiquitination sites on it; ubiquitination databases record sites on it; its protein half-life has been measured.
Gene: Protein-coding gene on chromosome 6 (163,414,000 to 163,578,592, forward strand). Ensembl gene ENSG00000112531.
Subcellular location: Nucleus; Cytoplasm; Nucleus (Isoform QKI5); Cytoplasm, cytosol (Isoform QKI6); Cytoplasm, cytosol (Isoform QKI7); Cytoplasm, Stress granule
Subcellular location (Human Protein Atlas): Nucleoplasm
Pathways (Reactome):
Disease: Signaling by BRAF and RAF1 fusions
Gene Ontology:
Molecular function: internal N(7)-methylguanine-containing RNA reader activity; mRNA binding; protein binding; RNA binding; mRNA 3'-UTR binding; nucleic acid binding
Biological process: intracellular mRNA localization; mRNA transport; regulation of epithelial to mesenchymal transition; regulation of macrophage differentiation; regulation of mRNA splicing, via spliceosome; spliceosome-depend formation of circular RNA; vascular associated smooth muscle cell differentiation; microglia differentiation; negative regulation of 3'-UTR-mediated mRNA stabilization; negative regulation of cold-induced thermogenesis; regulation of astrocyte differentiation; mRNA processing; mRNA stabilization; myofibroblast contraction; negative regulation of translation; positive regulation of oligodendrocyte differentiation; regulation of cell development; regulation of multicellular organismal development
Cellular component: cytoplasm; nucleoplasm; nucleus; cytoplasmic stress granule; cytosol; synapse
Genetic constraint (gnomAD): Loss-of-function variants: 8 observed, 32.17 expected, observed/expected ratio (o/e) 0.25, 90% interval 0.14 to 0.45. The synonymous counts are far from expectation, so gnomAD's model fits this gene poorly and the ratio says little. Missense variants: 213 observed, 413.5 expected, observed/expected ratio (o/e) 0.52, 90% interval 0.46 to 0.58. Synonymous variants: 200 observed, 155.94 expected, observed/expected ratio (o/e) 1.28, 90% interval 1.14 to 1.44.
Cancer hallmarks: escaping programmed cell death (promotes or suppresses); suppression of growth (promotes)
Homologues: Orthologues: mouse Qki (100% identical), rat Qki (99% identical), chimpanzee QKI (99% identical), macaque QKI (98% identical), dog QKI (92% identical), pig QKI (92% identical), tropical clawed frog qki (87% identical), zebrafish qkib (87% identical), rabbit QKI (86% identical), guinea pig QKI (70% identical), Drosophila melanogaster qkr54B (23% identical), Drosophila melanogaster qkr58E-1 (23% identical), and 6 more. Paralogues in human: KHDRBS1 (35% identical), KHDRBS2 (35% identical), KHDRBS3 (32% identical), SF1 (31% identical).
Diseases named in the same sentence as QKI in open-access papers:
QKI is named in the same sentence as 127 diseases in open-access papers, as found by Europe PMC text mining. Sharing a sentence is not in itself a finding about the gene and the disease. The quoted sentences say what the papers report.
lung carcinoma (28 papers, 2014 to 2025). "In lung cancer, QKI (QKI-5) suppresses cancer-associated aberrant splicing of NUMB to prevent the activation of Notch signal and tumor proliferation." (PMID 38485986, 2024). "Other interesting targets for AS regulation by QKI in lung cancer are ESYT2 and ADD3, which encode proteins involved in cytoskeleton organization." (PMID 34065983, 2021). "Nevertheless, QKI expression is often decreased in NSCLC and loss of QKI function can thus be associated with lung cancer." (PMID 34065983, 2021). "For instance, lower QKI expression in lung cancer was associated with a poorer prognosis, while QKI overexpression inhibited the malignant proliferation of lung cancer cells in vivo and in vitro by preventing Notch signaling pathway activation." (PMID 32931453, 2020). "Compared with normal tissues, the expression of QKI is significantly reduced in lung cancer, which is associated with a poor prognosis." (PMID 32653017, 2020). "Recently, QKI was shown to be aberrantly expressed in lung cancer and associated with poor prognosis in two independent studies, but none of these studies investigated circRNA expression." (PMID 28991235, 2018). "In summary, our data indicate that down-regulation of QKI causes aberrant splicing in lung cancer and suggest a novel tumor suppression mechanism involving QKI-mediated repression of Notch signaling." (PMID 24722255, 2014). "We show that QKI is frequently down-regulated in lung cancer, and its down-regulation is significantly associated with a poorer prognosis." (PMID 24722255, 2014). "In addition, downregulated QKI is positively correlated with lung cancer progression and negatively associated with patient survival." (PMID 39897555, 2025). "QKI, one of the most downregulated AS factors in lung cancer, is associated with poor prognosis." (PMID 38302461, 2024). "Thus, U1 snRNA mutations have been associated with medulloblastomas, U2 SF3B1 mutations with blood cancers such as myelodysplasia or lymphocytic leukaemia, U5 Prp8 mutations with retinitis pigmentosa and QKI downregulation with lung cancer." (PMID 39273537, 2024). "Loss of QKI is correlated with a poor prognosis in lung cancer." (PMID 34127686, 2021). "Furthermore, increased QKI expression in tumor endothelial cells (TECs) was associated with significantly worse overall survival in lung cancer patients, suggesting QKI may be a clinically relevant therapeutic target to regulate tumor angiogenesis." (PMID 41222726, 2025). "Notably, QKI is frequently downregulated in lung cancer and associated with a poorer prognosis." (PMID 37603540, 2023). "Prior work in lung cancer demonstrated that tumor ECs have reduced miR-200 family expression, resulting in increased expression of all QKI isoforms." (PMID 41222726, 2025). "We have previously observed evidence that the tumor microvasculature has higher expression of all isoforms of QKI in both clinical and experimental lung cancer samples compared with matched normal lung endothelium." (PMID 41222726, 2025). "In lung cancer, the splicing factor QKI represses the inclusion of NUMB alternative exon through competing with a core splicing factor SF1, thereby inhibiting proliferation and Notch signaling." (PMID 36304260, 2022). "In lung cancer, QKI expression was significantly reduced, increasing in the abnormal splicing of num exon 11 to, in turn, activate the Notch signaling pathway and tumor cell proliferation." (PMID 34179079, 2021). "The RNA‐binding protein QKI is a key regulator of alternative splicing in lung cancer and has been frequently reported as downregulated in lung cancer." (PMID 32536039, 2020). "Recent two large scale analyses reported that QKI is a major regulator of alternative splicing in lung cancer, and downregulation of QKI protein is an independent factor for poor prognosis." (PMID 29064439, 2017).
lung carcinoma (continued). "For example, QKI was frequently down-regulated in lung cancer, and QKI-5 inhibited the proliferation and transformation of lung cancer cells." (PMID 26100984, 2015). "In this study, we characterized the RNA-binding protein QKI as a new critical regulator of alternative splicing in lung cancer and as a potential marker for prognosis." (PMID 24722255, 2014). "Taken together, our data reveal QKI as a critical regulator of splicing in lung cancer and suggest a novel tumor suppression mechanism involving QKI-mediated regulation of the Notch signaling pathway." (PMID 24722255, 2014). "In summary, our study demonstrates that QKI is a critical regulator of aberrant splicing in lung cancer and that the Notch signaling regulator, NUMB, is a key target of QKI in the control of cell proliferation." (PMID 24722255, 2014). "Our genome-wide analysis of QKI targets by RNA-Seq established QKI-5 as a master regulator of alternative splicing in lung cancer cells." (PMID 24722255, 2014). "Together, our data establish QKI as a critical regulator of splicing in lung cancer and present a new QKI/NUMB/Notch pathway in the regulation of cell proliferation." (PMID 24722255, 2014). "We also show that increasing QKI-5 levels in lung cancer cells suppresses cell proliferation and transformation both in vitro and in vivo, implicating that QKI is a potential drug target for the cancer treatment." (PMID 24722255, 2014). "Through RNA-Seq analysis, we identified QKI as a master regulator of alternative splicing in lung cancer cells." (PMID 24722255, 2014). "To understand the molecular basis for QKI function in lung cancer, we performed a genome-wide search for mRNA targets of QKI." (PMID 24722255, 2014). "However, QKI suppresses the growth and malignant transformation of lung cancer cells in both in vitro and in vivo models." (PMID 41282593, 2025). "Two of them, PATL1 and PRRC2B were discussed earlier; SENP7 is a marker of poor prognosis in colon cancer; SPAG9 is expressed in a variety of malignancies and regulated by QKI in lung cancer; UBR5 promotes postsurgical breast cancer lung metastases, and NSD1 exerts tumor suppressive functions." (PMID 39664813, 2024). "QKI has also been identified as a master regulator of alternative splicing in human lung cancer cell lines, but no significant statistical association was found between QKI expression and smoking status in lung tumors." (PMID 37521848, 2022). "A genome-wide analysis of mRNA splicing changes in NSCLC compared to matched non-malignant lung tissues revealed that a large fraction of the identified differential splicing events were targets for QKI, suggesting that QKI is a major regulator of AS in lung cancer." (PMID 34065983, 2021). "While QKI is found mutated in a subset of malignant gliomas, mutations in QKI are not frequently found in other cancers including lung cancer." (PMID 34065983, 2021). "Interestingly, several other studies have indicated that QKI can also play tumour suppressive roles, and in one case, QKI‐directed alternative splicing of NUMB has been shown to reduce growth of lung cancer cells in vivo." (PMID 29871889, 2018). "Since down-regulation of QKI is significantly associated with poor prognosis at early cancer stages, it indicates that QKI and its targets identified in this study may serve as earlier markers for lung cancer." (PMID 24722255, 2014). "Previous studies have shown that QKI binds upstream and downstream of SMARCA5, ZEB1 and NDUFB2 RNA to promote circRNA formation in lung cancer, prostate cancer, and hepatocellular carcinoma." (PMID 40263288, 2025). "SFs, including QKI, RBM4, RBM5, RBM6, RBM10, and SRSF1, were involved in the development of lung cancer, as SFs play a regulatory role in splicing." (PMID 33047900, 2020). "Abnormal expression of QKI and NOVA1 has been reported to participate in the development of lung cancer and colorectal cancer." (PMID 32939931, 2020).
lung carcinoma (continued). "Protein quaking (QKI), a splicing factor frequently downregulated in lung cancer and correlated with poor prognosis, selectively suppressed the inclusion of NUMB mRNA exon 12 to promote the expression of a NUMB isoform, thereby inhibiting proliferation and the Notch signalling pathway." (PMID 33685397, 2021). "Like QKI, RBM10 expression is significantly reduced in lung cancer cells." (PMID 32653017, 2020).
breast carcinoma (21 papers, 2018 to 2025). "Kaplan‒Meier survival analysis revealed that high QKI expression was associated with poor prognosis in patients with ER+ breast cancer in multiple datasets." (PMID 37524698, 2023). "Another example is the gene FLNB whose exon 30 was found to be skipped in the majority of tumors, which is consistent with previous findings that the skipping of this exon induces EMT, is associated with basal-like breast cancer, and is regulated by the RNA binding proteins QKI and RBFOX1." (PMID 38674106, 2024). "Notably, QKI mRNA and protein are downregulated in breast cancer and decreased QKI expression was significantly associated with ER, PR, and HER2 positive, non-basal-like breast carcinoma and non-triple-negative breast cancer." (PMID 36059653, 2022). "Significant downregulation of QKI has been noted in breast cancer relative to normal tissues, along with poor prognosis, which suggest its tumor-suppressor role." (PMID 41048341, 2025). "GAS5 suppressed breast cancer growth via IGF2BP2/QKI, and this inhibitory effect was modulated by FTO both in vitro and in vivo." (PMID 38782769, 2024). "QKI is an RNA binding protein that acts as a tumor suppressor in multiple tumors, including colon, lung, oral, prostate and breast cancers." (PMID 38782769, 2024). "In both breast tissue and breast cancer cell lines, we found the ratio of QKI-6 and QKI-7 to total QKI was higher in samples with greater total QKI mRNA levels." (PMID 38019605, 2024). "To assess this, we performed qRT-PCRs for each QKI isoform and total QKI mRNA on a panel of breast cancer cell lines and plotted the ratio of each isoform to total QKI against total QKI expression." (PMID 38019605, 2024). "miR-330-3p as lncTPT1-AS1 downstream and regulates QKI and thus inhibits the malignancy of breast cancer cells." (PMID 35874898, 2022). "Meanwhile, QKI expression is positively correlated with the survival of patients, suggesting the prognostic value of QKI in breast cancer patients." (PMID 36059653, 2022). "In their main cell culture system of breast cancer cell lines, QKI had a profound effect on mRNA splicing, suggesting that miR-200/miR-375/QKI control alternative splicing during EMT." (PMID 32645914, 2020). "This is consistent with the previous discovery that upregulation of QKI can induce de novo circRNA biogenesis in breast cancer cells." (PMID 31446897, 2019). "The RNA-binding protein Quaking (QKI) resulted in low levels of FOXO1 expression in breast cancer cells." (PMID 29796115, 2018). "To assess the relevance of QKI‐mediated alternative splicing during EMT to human cancers, we initially evaluated the relationship between QKI expression and specific splicing events in TCGA breast cancer RNA‐seq data." (PMID 29871889, 2018). "Since QKI‐5 is the major isoform in the breast cancer cells, we used the QKI‐5 3′UTR to test for direct miRNA targeting." (PMID 29871889, 2018). "We elucidated that GAS5 suppressed breast cancer growth via IGF2BP2/QKI, and this inhibitory effect could be attenuated by FTO." (PMID 38782769, 2024). "Finally, we investigated the biological functions of the FTO/GAS5/IGF2BP2/QKI axis in breast cancer." (PMID 38782769, 2024). "QKI expression was previously correlated with EMT in breast cancer cells." (PMID 38325381, 2024). "The nuclear localized QKI isoform, QKI-5, has previously been shown to influence mesenchymal features of breast cancer cells, including promoting an elongated cell morphology, increasing cell migration, and facilitating a mesenchymal alternative splicing program." (PMID 38019605, 2024). "In addition, knockdown or overexpression of IGF2BP2 or QKI reversed the effect of GAS5 on the proliferation of breast cancer cells, respectively." (PMID 38782769, 2024). "In ER+ breast cancer, QKI promotes the formation of circRNA-SFMBT2." (PMID 39479357, 2024). "Next, we explored the biological functions of the FTO/GAS5/IGF2BP2/QKI axis in breast cancer." (PMID 38782769, 2024).